CDK1 (cyclin dependent kinase 1)
Diseases named in the same sentence as CDK1 in open-access papers (continued):
Sharing a sentence is not in itself a finding about the gene and the disease.
tumor (continued). "Particularly noteworthy was the consistent and striking finding within the BRCA study: the expression levels of both CDK1 and DTL were markedly elevated in tumor samples compared to other conditions." (PMID 39567714, 2024). "As resident tumor macrophages expressing MKI67, CDK1, and CDC45, HMGB1, and others, Prolif-TAMs were likely pro-inflammatory, profibrotic, and promoting tumor progression." (PMID 39184073, 2024). "The expressions of miR-4516 were lower, while the expressions of Wnt 8B, DVL3, FOSL1, CDK1, CDK2, CCNA1, and CCNB1 were enhanced in tumor tissue compared to normal lung tissue in the human samples." (PMID 38930863, 2024). "Cyclin-Dependent Kinase 1 (CDK1) is a key regulator of cell cycle progression and its elevated expression participates in tumor development." (PMID 38842611, 2024). "A recent study has demonstrated that the overexpression of AURKA, CDK1, and PLK1 is positively correlated with tumor grades and stage." (PMID 38672246, 2024). "Other studies have described that UBE2C, along with the other signaling molecules such as AURKA, EMT, GRIK3, CDK1, and claudin 19, activates the WNT/β-catenin signaling pathway, thus altering tumor biology." (PMID 39479352, 2024). "Combined inhibition of Pin1 and CDK1 with sulfopin and RO3306 most effectively suppresses orthotopic tumor growth." (PMID 38167292, 2024). "We identified that CDK1 activates STAT3 to regulate tumor sphere formation and the expression of stemness-related genes CD44 and SOX2, as well as both CDK1 and STAT3, which are negatively correlated with the prognosis of PDAC patients." (PMID 37743465, 2023). "Studies have shown that the selective inhibition of CDK1, PBK, and CHEK1 arrests tumor progression in sarcomas, GBM, prostate, endometrial, and breast cancers by blocking the G2-M phase transition and promoting apoptosis." (PMID 38003585, 2023). "Results from our analysis also indicate that, among the thirty genes which are differentially expressed in OSCCs, seven of them (namely BRCA1, CCNE2, CDC25C, CDK1, CDK2, E2F1, and FANCD2) positively correlate with both tumor grade and HPV infection." (PMID 36768994, 2023). "Surprisingly, the mRNA levels of CDK1 and Cyclin A2 (CCNA2) were significantly higher in the tumor epithelial cells of EOCC tumor invasive margin compared to LOCC tumor invasive margin." (PMID 37964075, 2023). "CDK1, ECT2, EZH2, GJB2, GPR37, GPX2, and GPX8 mRNA expression was up-regulated in the tumor group (p < 0.001), whereas GPX3, HYAL1, and TLR4 mRNA expression was down-regulated in the tumor group (p < 0.001) compared with those in the normal group." (PMID 37689745, 2023). "We found that CDK1/PBK/CHEK1 overexpression drives the cell cycle, subsequently promoting GBM tumor progression." (PMID 38003585, 2023). "On the other hand, in KIRP, CDK1, CDK4, HIPK2 and MYC expression increased with the pathological and clinical stage of the tumor, whereas KLF4 decreased." (PMID 37047552, 2023). "The results revealed that AURKA, BIRC5, CCNB1, CDK1, CDKN3 and TYMS were significantly upregulated in tumor tissues." (PMID 37393234, 2023). "CDK1‐mediated phosphorylation is essential to activate USP29 toward TWIST1 and promote tumor progression in TWIST1 dependent manner." (PMID 36782089, 2023). "In conclusion, CDK1 is a promising member of the CDK family in LUAD and plays an essential role in tumor cell proliferation and immune microenvironment regulation." (PMID 36950551, 2023). "Whilst NU-6102 showed no activity (IC50 > 10 μM), probably due to its higher sensitivity towards CDK1, AUZ 454 exhibited considerable levels of anti-tumour activity in the range of μM, suggesting an abnormal behaviour of CDK2 in HGSC." (PMID 37120667, 2023). "According to The Cancer Genome Atlas (TCGA) and Clinical Proteomic Tumour Analysis Consortium (CPTAC), CDK1 is upregulated in many cancerous tissues compared to normal tissues, at both transcript and protein levels." (PMID 37898722, 2023).
tumor (continued). "The simultaneous inhibition of CDK1/PBK/CHEK1 will promote the cell cycle arrest, senescence, and apoptosis of GBM, suppressing tumor progression." (PMID 38003585, 2023). "As expected, OPC markers OLIG2, SOX9, and cell cycle genes CDK1, MKI67 are highest in the tumor core (early peak), while neuronal markers ZIC1, GABRA1, and mature oligodendrocyte marker MBP are highest in the GCL_N (late peak)." (PMID 36823172, 2023). "The result also showed that CDK1, CDK5, CDC20, CCNA2, CCNB1 and CCNB2 mRNA expression levels within tumor tissues were significantly increased compared with the adjacent normal tissues." (PMID 36605491, 2023). "We note multiple network connections between BUB1 and HDAC1, as well as connections between BUB1 and each of CDK1 (cell-cycle transition regulator) and APC (a tumor-suppressor protein within the Wnt signaling pathway)." (PMID 38030619, 2023). "CDK1 was an independent prognostic factor for LUAD and improved the ability to predict overall survival when combined with tumor stage." (PMID 36950551, 2023). "The immunohistochemistry result of subcutaneous tumor indicated that knockdown CLSPN significantly down regulated CCNA2, CCNB1, CDK1, CDK2 and Ki67 expression." (PMID 37268895, 2023). "The expression of CDK1, ECT2, GJB2, GPR37, GPX2, and GPX8 gene was up-regulated in the tumor group (p < 0.001), whereas the expression of TLR4 was down-regulated in the tumor group (p < 0.001) when compared with those in the normal group." (PMID 37689745, 2023). "The expression of CDK1, MKI67, TOP2A, and CEP55 was significantly higher in tumor tissue than in normal tissue." (PMID 38134110, 2023). "The expression levels of CDK1, SPC24, and HOXB7 were significantly higher in tumor tissues than in normal tissues." (PMID 36718148, 2023). "Many researchers have identified CDCA8 as a novel oncogene, which predicts a poor prognosis in HCC as well as promotes tumor proliferation via MEK/ERK, AKT/β-Catenin, and CDK1/cyclin B1 signaling." (PMID 37854038, 2023). "The results showed that high expression of CDK1 significantly affected OS and RFS in tumor patients." (PMID 36090896, 2022). "The baicalein derivatives remarkably inhibited the activity of CDK1/cyclin B kinase and the proliferation of MCF-7 tumor cells." (PMID 36003621, 2022). "These associations were also maintained at the protein level across tumor types; expression of proteins that most highly correlated with repstress score included CYCLINB1, CYCLINE1, CHK2, 4EBP1, phosphorylated CDK1 and PCNA." (PMID 36381660, 2022). "In terms of immune microenvironment, we found that the expressions of AURKA, CCNA2, CCNE1, CDK1, CHEK1, and PLK1 were negatively correlated with tumor immune infiltrating cells." (PMID 36483630, 2022). "In the case of HCC, miR-582-3p has been demonstrated to be downregulated, and its overexpression reduces cell proliferation and induces cell cycle arrest in the G0/G1 phase by targeting CDK1 and AKT3, suggesting it to be a tumor suppressor." (PMID 35609318, 2022). "In addition, we found that the expressions of AURKA, CCNA2, CCNE1, CDK1, CHEK1, and PLK1 were all positively correlated with TMB, which was consistent with previous research results, and there was a positive correlation between tumor dryness and tumor mutation burden." (PMID 36483630, 2022). "Given the functional mechanism and carcinogenic potential of CCNB1, CDK1, and PAICS miRNAs, these three genes' upstream miRNAs ought to be tumor suppressive." (PMID 36081668, 2022). "The Tumor Immune Dysfunction and Exclusion (TIDE) algorithm was used to predict the correlation between the expression of CDK1 and the response of immune checkpoint inhibitors." (PMID 36078096, 2022). "In conclusion, we constructed a five DEGs (CCNB2, CDK1, DTL, GMNN, and UBE2C)-based prognostic signature for ACC and first identified GMNN as a novel tumor biomarker for predicting the malignant progression, mitotane efficacy, and prognosis of ACC." (PMID 36539849, 2022).
tumor (continued). "Simultaneously suppressing CDK1 and boosting ID2 with apigenin strongly repressed tumor growth in a mouse model." (PMID 35729325, 2022). "The comparison results showed that the mRNA expression levels of CDK1 and P2RX4 in PTC tissues were significantly higher than those in non-tumor thyroid tissues." (PMID 36333684, 2022). "We then examined the expression of 9 model genes in single cells and found that CDK1, AURKB, CCNA2, and CHEK1 are mainly expressed in CD4 cells, while PRKAA2, CDK5, and PRKCD are mainly expressed in tumor cells." (PMID 36120466, 2022). "CDK1 is highly expressed in HCC cells and activates the cell cycle pathway to promote tumor cell proliferation." (PMID 35399722, 2022). "Compound 2a displayed a better inhibition rate (96.7%) than flavopiridol (90.0%) against MCF-7 tumor cell proliferation at a concentration of 50 μg/ml, and comparable to CGP74514A, a selective CDK1 inhibitor (96.7%)." (PMID 36003621, 2022). "CDK1, AURKB, CCNA2, and CHEK1 were highly expressed in immune cells, suggesting that histone phosphorylation is closely related to the tumor immune environment." (PMID 36120466, 2022). "Further, the relationship between the expression of CDK1, HSP90AA1, and tumor stage (pathological stage plot) in lung cancer patients was evaluated using GEPIA." (PMID 35330393, 2022). "qPCR experiments verified that the expressions of MAP7, CDK1, PPP3R1, PRKC1, CCND1 and HDAC1 genes were indeed altered in AT/RT tumor tissue." (PMID 35524230, 2022). "CDK1/CCNB1 were crucial cell cycle proteins, regulating mitochondrial bioenergetics in cell cycle progression and tumor resistance." (PMID 35155425, 2022). "The expression profiles of genes in the first cluster across all tumours (TOP2A, CDK1, BIRC5, GPC3, IGF2 and AFP) were strongly correlated." (PMID 36345011, 2022). "Of the SAC genes overexpressed in the OB tumor cells, TKK, PLK1, CDK1, BUB1 and BUB1B have been shown to play a role in radiosensitivity." (PMID 36482431, 2022). "It was found that CDK1 together with CXCL8 participate in G2M checkpoint, tumor proliferation, EMT, and other pathways." (PMID 36078096, 2022). "In different datasets, based on all or most tumor types, high CDK1 expression levels suggested a poor prognosis for tumor patients, affecting OS, DFS, DMFS, RFS, DRFS, DSS, and MFS survival progression in tumor patients." (PMID 36090896, 2022). "Correlation analysis results also indicated that CDK1 expression was related to TNM stage (P < 0.001), tumor status (P < 0.001) and pathological stage (P < 0.001)." (PMID 36184616, 2022). "The results suggest that CDK1 was positively correlated with PI3K/Akt/mTOR pathway, cellular hypoxia response, EMT related genes, G2M checkpoint, and tumor proliferation, while negatively correlated with angiogenesis." (PMID 36078096, 2022). "Cyclin-dependent kinase-1 (CDK1) phosphorylates HIF-1α at serine 668, increasing the expression of HIF-1α and its target genes and boosting tumor angiogenesis, proliferation, and growth." (PMID 36338690, 2022). "Upon CDK1 overexpression, YYFZBJS’s ability to induce apoptosis and cell cycle arrest in the tumor cells was weakened." (PMID 36457504, 2022). "The hub genes TOP2A, CDK1, and BIRC5 formed the top cluster with expression in 80–90% of the tumours." (PMID 36345011, 2022). "In tumor cells, circ-CCNB1 has been shown to bind to both CCNB1 and CDK1, thereby inhibiting the formation of the CCNB1-CDK1 complex and its entry into the nucleus, resulting in the inhibition of tumor growth and extension of mouse viability." (PMID 35731831, 2022). "To ascertain the new tumor biomarkers expressed in LUAD, we constructed a CDK1-related ceRNA network." (PMID 35406786, 2022). "In this study, a systemic analysis was performed to reveal CDK1, CCNB2, and CDC25A as the hub genes; the expression of these genes increased in tumor tissues and predicted poor prognosis in LUAD." (PMID 34446056, 2021).
tumor (continued). "Our findings are supported by the results from a recent study that activation of cyclin-dependent kinase 1 (CDK1) phosphorylated HIF-1α protein and led to tumor growth." (PMID 33920906, 2021). "By using TCGA and THPA databases, we found five genes, CDK1, CDC20, CCNB1, CENPF, and MAD2L1, that were related to the early diagnosis, tumour stage, and poor outcomes of HBV-HCC." (PMID 34603487, 2021). "The SNHG4/miR-590-3p/CDK1 axis influences the cell cycle to modulate CRC cell proliferation and subcutaneously transplanted tumor growth." (PMID 33744866, 2021). "Together, these findings show that combined BCL-XL and CDK1/2/4 targeting, while perturbing cell cycle regulators, leads to a combinatorial depletion of survival and RTK/AKT signals, restoring FOXO3a tumour suppression actions." (PMID 34646365, 2021). "In order to develop effective therapies targeting CDK1 inhibition, clinical trials should measure the CDK1 tumour expression of PDAC patients before and during treatment in order to keep track of how CDK1 expression is affected by the therapy." (PMID 34503199, 2021). "The enhanced inhibition of HIF1α by combined targeting of CDK1 or CDK4/6 and HSP90 was observed in multiple tumor cell lines." (PMID 34686682, 2021). "Our findings suggest that many of patients who had elevated expression of tumor‐specific signatures such as ESR1, AR, VEGF, AKT1/2/3, CCND1, CDK1, and MMP9 had significantly poorer disease‐free survivals compared with the remaining subgroups." (PMID 33275817, 2021). "The tumor markers CDKN2A and KRT7 were the most upregulated genes with fold changes 10.7 and 4.8, respectively, while markers for proliferation (MELK, CDK1, MKI67, CCNB2, BUB1, FOXM1, CDKN3) had fold changes spanning from 2.0–2.7." (PMID 35008799, 2021). "And the heatmap of the enriched genes in the pathways indicated that key genes involving tumor proliferation such as BRCA1, CDK1, and CCNB1 et, al." (PMID 35095481, 2021). "Then, we inhibited CDK1 kinase activity with the CDK1-specific inhibitor RO-3306 and found that the ability of highly expressed ABCC5 to promote tumor proliferation and migration was also inhibited when CDK1 kinase activity was inhibited." (PMID 33994848, 2021). "From 370, 445, and 455 different tumor studies, TTK, NEK2, and CDK1 gene expression data were collected." (PMID 34072728, 2021). "Upregulated genes included several genes involved in the control of the cell cycle like E2F2, cyclin-dependent kinase 1 (CDK1) and MCM2 but also cytokine gene network with crucial effects on inflammation and tumor immunology as well." (PMID 33499054, 2021). "In COAD, CDK-1 and CDK-4 clearly shows significant positive correlations with tumor purity while in READ, only CDK-4 was positively correlated with tumor purity." (PMID 33732631, 2021). "Mechanistically, we show that, co-targeting of BCL-XL and CDK1/2/4 synergistically inhibited cell viability by combinatorial depletion of survival and RTK/AKT signals, and concomitantly restoring FOXO3a tumour suppression actions." (PMID 34646365, 2021). "In fact, 3 of top 5 kinase genes include CDK1, PLK1, and AURKB were significantly highly expressed in tumor tissues and significantly related to the overall survival of LUAD." (PMID 33178836, 2020). "A review of the literature found that six of the 12 upregulated genes (KPNA2, CDK1, TARBP1, PRC1, FEN1, and MCM6) were overexpressed in HCC tissue compared to levels in non-tumor tissue based on immunohistochemical staining." (PMID 32213663, 2020). "TCGA dataset mining was performed using UALCAN to shown that abnormal expression of the hub genes, including CDK1, VEGFA, PRDM10, RUNX1, CDK6, HSP90AA1, and MYC, were significantly up-regulated between ESCA primary tumor and normal tissues." (PMID 32662828, 2020).
tumor (continued). "For example, alterations in CDK1 and CDK2 enzyme kinetics parameters will disrupt the regular cell cycle; the in vitro tumor cell proliferation dynamics follows a fractal structure different from normal oscillatory dynamics." (PMID 33297998, 2020). "In fact, 3 of the top 5 kinase genes include CDK1, PLK1, and AURKB, were significantly highly expressed in tumor tissues and significantly related to the overall survival of LUAD." (PMID 33123291, 2020). "Next, we further identified 21 anti-tumor drugs (e.g., Cladribine, Gallium nitrate, Dinaciclib, Alvocidib, Suramin) targeting RRM2, CDK1 and CCNA2." (PMID 33083112, 2020). "In fact, PLK1, CDK1, and AURKB were significantly upregulated in tumor tissues, by contrast, ATM was markedly downregulated expressed in tumor tissues, except CDK2." (PMID 33292231, 2020). "Our study successfully linked the LMNA gene expression and the expression of P16 and CDK1 in HepG2 and 293T cell lines, providing a basis for exploring the relationship between LMNA gene and tumorigenesis in various tumour types." (PMID 32896989, 2020). "E2F8 overexpression in HCC facilitated the tumor occurrence and aggressiveness through activating a E2F1/Cyclin D1 signaling pathway to regulate the G1-S transition or transcriptionally suppressing CDK1 to induce hepatocyte polyploidization." (PMID 31990034, 2020). "This was confirmed by RNAscope analysis performed on three out of six genes (BIRC5, CDK1, and PBK), showing their predominant expression on tumor cells of NB patients." (PMID 33239635, 2020). "A study found that in renal cell carcinoma, the down-regulation of Aurora A kinase induces a decrease in the expression of cyclin B1/CDK1 complex, and inhibits cell proliferation and metastasis by blocking ERK activity, thereby exerting anti-tumor effects." (PMID 32518522, 2020). "For instance, DMT1-imported iron was shown to activate cyclin-dependent kinase 1 (CDK1) and JAK1/STAT1, contributing to colorectal tumorigenesis, and DMT1 inhibitor impeded tumor growth in vivo." (PMID 33287315, 2020). "The expression of Cyclin B1 and CDK1 was reduced in tumors from BITC-treated mice, which resulted in the suppression of tumor growth." (PMID 33263014, 2020). "The results of the PDX tumor tissue model indicated that in the anlotinib group the phosphorylation levels of VEGFR2 and AKT and the protein levels of the CDK1 group were also significantly decreased, compared with the control group." (PMID 32709873, 2020). "It is well-established that CDK1 is a key molecule in the progression of mitosis, and thus PKMYT1 is thought to play important roles in the regulation of the cell cycle and tumor biology." (PMID 32180804, 2020). "Abundance of our three key proteins INPP4B, CDK1, and ERBB2 across tumors of different ER status, tumor grade, and HER2 status correlated well with their respective transcript levels." (PMID 31315058, 2019). "Consistent with the expression results analyzed by ONCOMINE, the expression levels of CDK1, CCNB1, CCNB2, MAD2L1, and TOP2A assessed by TCGA data were all upregulated in tumor tissues compared with the normal controls (all P < 0.05)." (PMID 31886163, 2019). "We found that in the absence of IFITM3, phosphorylation of P38-AMPK was significantly weakened and the phosphorylation level of CDK1 (CDC2) was also decreased, confirming the effect of IFITM3 on tumor cell proliferation." (PMID 31273201, 2019). "Western blotting of the xenograft tumour tissues from the nude mouse model showed that overexpression of ABHD11‐AS1 increased the expression of cyclin D1, CDK1, CDK2, CDK4, Bcl‐xl and VEGFA and decreased the expression of p16." (PMID 29799152, 2018).